WNT2 (Wnt family member 2)
Diseases named in the same sentence as WNT2 in open-access papers (continued):
Sharing a sentence is not in itself a finding about the gene and the disease.
cervical carcinoma (8 papers, 2016 to 2025). A carcinoma arising from either the exocervical squamous epithelium or the endocervical glandular epithelium. "WNT2 expression is up-regulated in cervical cancer and is associated with tumor size, cell motility and invasion." (PMID 31366565, 2019). "The Association between WNT2 Expression Level and Clinicopathological Characteristics of Patients with Early-stage Cervical Cancer." (PMID 27513465, 2016). "WNT2 overexpression in cervical cancer was associated with β-catenin activation and induction of EMT, which further contributed to metastasis in cervical cancer." (PMID 27513465, 2016). "Taken together, WNT2 overexpression in cervical cancer is associated with β-catenin activation and induction of EMT, which further contributes to the metastasis of cervical cancer." (PMID 27513465, 2016). "This study explored the expression and underlying mechanism of WNT2 in PLNM of cervical cancer." (PMID 27513465, 2016). "It has been found in cervical cancer that hsa-miR-1305 regulates the Wnt/β-catenin pathway by binding to Wnt2 to promote cell proliferation, migration, and invasion." (PMID 33664765, 2020). "WNT2 expression level in cervical cancer was detected using western blotting, quantitative PCR, and immunohistochemistry." (PMID 27513465, 2016). "In this study, we investigated the expression and biological significance of WNT2 in clinical samples from cervical cancer patients and a cervical cancer cell line." (PMID 27513465, 2016). "WNT2 was upregulated in 51.3% (161/314) of paraffin-embedded cervical cancer tissues." (PMID 27513465, 2016). "Both WNT2 mRNA and protein expression was upregulated in cervical cancer." (PMID 27513465, 2016). "WNT2 might be an identifying biomarker of PLNM for early cervical cancer, and a new potential therapeutic target." (PMID 27513465, 2016). "Finally, we present a clinical correlation, where high WNT2 expression in human cervical cancer tissue specimens strongly correlates with cytoplasmic and nuclear accumulation of β-catenin and increased metastasis potential." (PMID 27513465, 2016). "However, the relationship between WNT2 expression and lymph node metastasis in cervical cancer, and the involved mechanism remains largely unknown." (PMID 27513465, 2016). "A previous study also revealed that downregulating WNT2 significantly suppressed cell motility and invasion and reversed epithelial–mesenchymal transition (EMT) progression in cervical cancer." (PMID 34900703, 2021). "For example, wnt2, a member of the WNT gene family, is highly expressed in cervical cancer samples, and WNT signaling is normally involved in the development and progression of various cancers." (PMID 34900703, 2021). "Most importantly, PLNM and WNT2 expression level were independent prognostic factors for poor OS and DFS rates in patients with early-stage cervical cancer." (PMID 27513465, 2016). "In view of these findings, we believe that WNT2 is a potential novel predictor of PLNM and a promising therapeutic target in cervical cancer." (PMID 27513465, 2016). "As the reported pelvic lymph node micrometastasis rate is 15% in patients with early-stage cervical cancer, it is highly possibly that the actual accuracy of predicting PLNM could be 51% (36% + 15%) by detecting WNT2 expression." (PMID 27513465, 2016). "Both WNT2 protein expression and mRNA expression were upregulated in the SiHa cells and in cervical cancer specimens compared with that in the adjacent noncancerous tissues." (PMID 27513465, 2016). "In this study, we demonstrate that both mRNA and protein level of WNT2 expression is upregulated in cervical cancer and in comparison with that in the paired adjacent noncancerous cervical tissues for the first time." (PMID 27513465, 2016). "WNT2 might be a novel predictor of PLNM and a promising prognostic indicator in cervical cancer." (PMID 27513465, 2016).
depression (6 papers, 2013 to 2023). "MiR-221 has been identified to be closely associated with the progression of depression via targeting the Wnt2/CREB/BDNF axis in hippocampal neurons in a CUMS model." (PMID 33927285, 2021). "MiR‐199a‐5p can target WNT2 to enhance the developments of depression by regulating the CREB/BDNF signaling." (PMID 34333859, 2021). "miR‐199a‐5p can target WNT2 to enhance the developments of depressions through the regulations of CREB/BDNF signaling." (PMID 34333859, 2021). "MiR‐199a‐5p can target WNT2 to enhance the development of depression through regulation of the CREB/BDNF signaling." (PMID 34333859, 2021). "All these results indicated that downregulation of miR-383 efficiently reduced CUMS-induced depression-like behaviors in rats by targeting Wnt2." (PMID 33927285, 2021). "The specific roles of miR-383 and Wnt2 in the development of depression-like behaviors of CUMS-induced rats were then explored." (PMID 33927285, 2021). "Our above experiments showed that CRS induces a synchronous reduction in Wnt2 and Wnt3, and that Wnt2 and Wnt3 participate in depression-like behaviors." (PMID 27622936, 2016). "Second, we found that Wnt2 or Wnt3 was sufficient for buffering CRS-induced depression-like behaviors." (PMID 27622936, 2016). "Knocking down Wnt2 or Wnt3 in the VH led to impaired Wnt/β-catenin signaling, neurogenesis deficits and depression-like behaviors." (PMID 27622936, 2016). "Our results suggested that the effects of overexpressing Wnt2 and Wnt3 more specifically resulted in a reversal of stress-induced depression-like behaviors." (PMID 27622936, 2016). "Taken together, our results demonstrated that Wnt2 or Wnt3 in the VH is necessary and sufficient for alleviating depression-like behaviors." (PMID 27622936, 2016). "Particularly Wnt2 expression was reported to be highly elevated in the rat hippocampus, and the viral overexpression of Wnt2 was sufficient to produce antidepressant-like behavioral actions in an animal model of depression." (PMID 24403870, 2013). "Several different anti-depressant drugs increase the expression of Wnt2, and viral-mediated overexpression of Wnt2 in the hippocampus alleviates depressive-like symptoms in some animal models of depression." (PMID 23639831, 2013). "Evidence has suggested that elevated miR-199a-5p levels could regulate depression by targeting Wnt family member 2 (Wnt2) signaling to brain-derived neurotrophic factor (BDNF)." (PMID 37505566, 2023). "The expression levels of miRNAs were detected by qRT-PCR, and the expression levels of Wnt2, depression-impacted proteins (GFAP, BDNF, CREB), brain neurotransmitters (5-HT, NE, DA) and apoptosis-related proteins (Bax and Bcl-2) were evaluated by qRT-PCR and western blot." (PMID 33927285, 2021). "In summary, our results demonstrated that downregulation of miR-383 could efficiently reduce depression-like behavior in CUMS-induced rats through directly promoting the expression of Wnt2, providing a novel therapeutic target for MDD treatment." (PMID 33927285, 2021). "In contrast, overexpression of Wnt2 or Wnt3 reversed CRS-induced depression-like behaviors." (PMID 27622936, 2016). "We next tested whether overexpressing Wnt2 or Wnt3 in the VH is sufficient for alleviating CRS-induced depression-like behaviors." (PMID 27622936, 2016). "Our results showed that CRS could selectively decrease the expression of Wnt2 and Wnt3, so we next investigated whether endogenous Wnt2 and Wnt3 are functionally related to depression-like behaviors." (PMID 27622936, 2016). "Importantly, the screening of small molecule compounds to increase levels of Wnt2 or Wnt3 could be a method for identifying potential new targets for interventions for depression." (PMID 27622936, 2016). "Taken together, our study indicates essential roles for Wnt2 and Wnt3 in CRS-induced depression-like behaviors and antidepressant." (PMID 27622936, 2016).
depression (continued). "Moreover, multiple studies have shown that BDNF is both necessary and sufficient for anti-depressant drug action, which leads to the interesting possibility that BDNF-mediated regulation of Wnt2 expression may be an important mechanistic link in the alleviation of symptoms during depression." (PMID 23639831, 2013). "Our results demonstrated that overexpressing Wnt2 or Wnt3 was sufficient for alleviating CRS-induced depression-like, but not anxiety-like behaviors." (PMID 27622936, 2016). "The selective reduction of Wnt2 and Wnt3 expression in the VH following CRS suggested that Wnt2 and Wnt3 may play roles in CRS-induced depression-like behaviors." (PMID 27622936, 2016). "Together, our results suggested that knockdown of Wnt2 or Wnt3 expression in the VH could mimic CRS-induced depression-like, but not anxiety-like behaviors." (PMID 27622936, 2016). "Moreover, we found that knockdown of Wnt2 or Wnt3 could mimic the depression- but not anxiety-like behaviors." (PMID 27622936, 2016).
esophageal squamous cell carcinoma (6 papers, 2019 to 2025). Esophageal squamous cell carcinoma (ESCC) is a type of esophageal carcinoma (EC) that can affect any part of the esophagus, but is usually located in the upper or middle third. "This is because Wnt2 expression levels in CAFs specifically already have been shown to be associated significantly with lymph node metastasis and prognosis of advanced CRCs,27,28 as well as esophageal squamous cell carcinomas." (PMID 37085135, 2023). "In esophageal squamous cell carcinoma, CAFs secrete WNT2 to inhibit the SOCS3/p‐JAK2/p‐STAT3 pathway, thereby suppressing CD8+ T‐cell activation." (PMID 41164803, 2025). "Downregulation of miR-30a-3p/5p promoted cell proliferation of esophageal squamous cell carcinoma through targeting Wnt2 and Fzd228." (PMID 33927285, 2021). "In a related study of primary esophageal squamous cell carcinoma (ESCC), we found that WNT2+ CAFs were negatively correlated with CD8+ T cells." (PMID 36759842, 2023). "In esophageal squamous cell carcinoma (ESCC), CAF‐derived WNT2 inhibits DC differentiation through the SOCS3/p‐JAK2/p‐STAT3 signaling cascade, thereby suppressing immune responses." (PMID 41164803, 2025).
glioblastoma (6 papers, 2019 to 2025). The most malignant astrocytic tumor (WHO grade IV). "A previous study demonstrated that up-regulating SNHG9 was associated with poor prognosis in glioblastoma, as this lncRNA promoted tumor cell proliferation via regulating Wnt2 and miR-199a-5p." (PMID 35887228, 2022). "Mechanistically, SNHG9 downregulates miR-199a-5p, leading to the upregulation of the Wnt2 axis in glioblastoma cells." (PMID 33652661, 2021). "SNHG9 is overexpressed in glioblastoma and upregulate Wnt2 by downregulating miR-199a-5p to promote the proliferation of cancer cells." (PMID 32738890, 2020). "Small nucleolar RNA host gene 9 (SNHG9), a recently identified lncRNA, has been reported to interact with Wnt2 to participate in glioblastoma." (PMID 32738890, 2020). "As SNHG9 can promote the expression of Wnt2 in glioblastoma, we speculated that downregulation of SNHG9 may also lead to inactivation of the WNT signaling in OA." (PMID 32738890, 2020). "Moreover, in glioblastoma, Wnt2 regulates glioblastoma cell growth and aerobic glycolysis." (PMID 32983993, 2020).
endometrial carcinoma (5 papers, 1997 to 2023). A malignant tumor arising from the epithelium that lines the cavity of the uterine body. "As observed from the results of the model, the risk score has the greatest influence on predicting the survival outcome, indicating that the risk model based on the WNT2 and WNT10A genes can better predict the prognosis of endometrial cancer." (PMID 34565373, 2021). "Wnt2, 3 and 5a mRNAs were also lower in endometrial carcinoma compared with normal endometrium." (PMID 9099960, 1997). "The WNT4 mRNA level was lower while WNT2, WNT3, and WNT5A mRNA levels were higher in endometrial carcinoma in comparison to normal endometrium." (PMID 26366420, 2015). "Also WNT2, WNT3, WNT4, and WNT5A genes expression was higher in normal human primary epithelial and stromal endometrial cultures compared to endometrial carcinoma cell lines, what suggest their participation in endometrial neoplasia." (PMID 26366420, 2015). "In contrast, not upregulation but downregulation of WNT-4, WNT-2, WNT-3, and WNT-5A was found to be important for endometrial cancer development." (PMID 37176048, 2023). "In contrast, in four endometrial carcinoma cell lines (RL95-2, HEC-1-A, AN3 CA and Ishikawa), Wnt2 and Wnt3 mRNAs were absent." (PMID 9099960, 1997).
preeclampsia (5 papers, 2009 to 2023). Preeclampsia is a hypertensive disorder of pregnancy that is characterized by new-onset hypertension with proteinuria presenting after 20 weeks of gestation, and depending on mild or severe forms may initially present with severe headache, visual disturbances, and hyperreflexia. "Although the clinical status of the placentas did not appear to be related to the methylation pattern of EPHB4 and WNT2 in human, a phenotypic effect of these MAP genes on the human placenta cannot be excluded as only two clinical features, IUGR and preeclampsia were evaluated." (PMID 19838307, 2009).
prostate carcinoma (5 papers, 2009 to 2025). A carcinoma that arises from epithelial cells of the prostate gland. "Katoh reported high Wnt-2 in primary prostate cancer tumors." (PMID 35201496, 2021).
liver fibrosis (4 papers, 2017 to 2024). "Ursodeoxycholic acid (UDCA), for instance, can alleviate liver fibrosis by promoting liver regeneration through the activation of the ID1-Wnt Family Member 2 (WNT2)/hepatocyte growth factor (HGF) pathway." (PMID 39199400, 2024). "Our study found that the expression of Wnt genes (Wnt1, Wnt2, Wnt3, Wnt3a and Wnt5a) was upregulated, and Wnt pathway signalling in hepatocytes was active during the progression of schistosomiasis-induced liver fibrosis." (PMID 28331224, 2017).
lymph node metastasis (4 papers, 2016 to 2025). "CAFs-derived Wnt2 showed significant association with lymph node metastasis and short median survival time (Wnt2-positive ESCC vs Wnt2-negative ESCC, 16 vs. 51 months)." (PMID 26822225, 2016). "CAF-derived Wnt2 was significantly associated with lymph node metastasis." (PMID 37927475, 2023). "For instance, studies have shown that WNT2, secreted by tumor-associated fibroblasts, drives tumor cell proliferation and invasion, particularly in WNT2-positive ESCC cases, which are associated with aggressive disease and lymph node metastasis." (PMID 39936971, 2025). "In our cohort, it is more meaningful that the experiment found high WNT2 expression in 20 cases of lymph node metastasis, where the positive expression rate was 91% (20/22)." (PMID 27513465, 2016). "There was a significant correlation between WNT2 expression level and prognostic risk factors such as lymphovascular space involvement (LVSI, P = 0.001), positive parametrium (P = 0.031), and most importantly, lymph node metastasis (P < 0.0001)." (PMID 27513465, 2016).
myocardial infarction (4 papers, 2019 to 2025). Gross necrosis of the myocardium, as a result of interruption of the blood supply to the area, as in coronary thrombosis. "To determine the clinical relevance of Wnt2 in cardiac I/R injury, we evaluated dynamic changes in serum Wnt2 levels in patients with acute myocardial infarction (AMI) before and after percutaneous coronary intervention (PCI)." (PMID 41397965, 2025). "Indeed, Analysis of the expression of Wnt proteins indicated that Wnt-2, Wnt-4, Wnt-10b, and Wnt-11 were significantly upregulated 5 days after myocardial infarction." (PMID 36072583, 2022). "When focusing on the early post-myocardial infarction (MI) phase, quantitative analyses of Wnt protein expression have unveiled notable upregulation of Wnt-2, Wnt-4, Wnt-10b, and Wnt-11 five days after MI." (PMID 38139379, 2023). "For example, a mouse model of myocardial infarction showed the dysregulation of expression of WNT2, -4, -7b, -10b and -11 as well as FZD1, -2, -5, -8 and -10, and mice mutants for Dvl1 are more susceptible to infarct rupture after induction of myocardial infarction." (PMID 31382613, 2019). "Here, we show that the downregulation of serum Wnt2 levels in acute myocardial infarction (AMI) patients following reperfusion therapy, and Wnt2 levels are inversely correlated with the levels of myocardial injury markers (cTnT and CK-MB)." (PMID 41397965, 2025).
osteoporosis (4 papers, 2007 to 2022). A condition of reduced bone mass, with decreased cortical thickness and a decrease in the number and size of the trabeculae of cancellous bone (but normal chemical composition), resulting in increased fracture incidence. "Meanwhile, astragalus polysaccharide (ASP) can effectively alleviate oxidative stress-mediated osteoporosis in ovariectomized rats by regulating the FoxO3a/Wnt2/β-catenin pathway." (PMID 36188607, 2022). "APS can effectively alleviate oxidative stress-mediated osteoporosis in ovariectomized rats, which may be related to its regulation of FoxO3a / Wnt2 / β-catenin pathway." (PMID 31166463, 2019). "Astragalus polysaccharide can effectively alleviate oxidative stress-mediated osteoporosis in ovariectomized rats, which may be related to its regulation of FoxO3a/Wnt2/β-catenin pathway." (PMID 31166463, 2019). "Furthermore, APS activated the expression of Wnt2, β-catenin, and LRP5 genes and inhibited oxidative stress in deovulated rats to reduce osteoporosis." (PMID 35877777, 2022).
atherosclerosis (3 papers, 2020 to 2023). A disease characterized by the build-up of fatty material and calcium deposition in the arterial wall resulting in partial or complete occlusion of the arterial lumen. "Mice fed on a high-fat Western-type diet expressed high concentrations of Wnt2 protein in atherosclerotic lesions, suggesting that the Wnt/β-catenin pathway also contributes to atherosclerosis." (PMID 37555575, 2023). "Thereby, targeting Wnt2 to prevent or attenuate plaque progression and induce regression of the EndMT process will become a novel strategy to cure atherosclerosis." (PMID 34901211, 2021). "An interesting question is whether a Wnt2 antibody would be beneficial in treating atherosclerosis since Wnt2 is a secreted protein and can be targeted with antibodies." (PMID 34901211, 2021). "Whether Wnt2 antibodies have a beneficial role in treating atherosclerosis will be addressed in our future studies." (PMID 34901211, 2021). "The migration promoting effect of WNT2 is well documented in CAFs and smooth muscle cells in atherosclerosis, though to the best of our knowledge there is so far no report available on effects of WNT2 on EC migration." (PMID 31667643, 2020). "As reported, in adults, Wnt2 enhances VSMC migration and intimal thickening in vivo; however, its role in atherosclerosis is not well-characterized." (PMID 34901211, 2021).
colon adenocarcinoma (3 papers, 2015 to 2022). "Only KLK6, COL11A1, and WNT2 has been found to be suitable prognostic predictors for colon adenocarcinoma." (PMID 35883559, 2022). "We found that, among 19 Wnt ligands, WNT2 and WNT5A are highly upregulated in colon mucinous adenocarcinoma, rectal adenocarcinoma, colon adenocarcinoma, and cecum adenocarcinoma." (PMID 26484565, 2015).
colorectal adenoma (3 papers, 2020 to 2021). An adenoma that arises from the colon or rectum. "SI-NETs were devoid of CFTR and WNT2 expression, whereas both genes were expressed in the adenocarcinomas and colorectal adenomas of the deletion carriers." (PMID 34274970, 2021). "Another analysis demonstrated that Wnt2 was upregulated in the progression from colorectal adenoma to carcinoma, and in situ hybridization showed that Wnt2 was expressed predominantly in macrophages in the lamina propria/stroma regions." (PMID 32923386, 2020).